CXCL10 (C-X-C motif chemokine ligand 10)
Diseases named in the same sentence as CXCL10 in open-access papers (continued):
Sharing a sentence is not in itself a finding about the gene and the disease.
tumor (continued). "We found that when neutrophils were co-cultured with cisplatin-pretreated tumor cells, they expressed significantly higher levels of chemokines, such as CXCL9, CXCL10, and CXCL11, which could be key regulators of recruitment of T cells into tumor tissues." (PMID 35784745, 2022). "In this study, we provide evidence that circulating levels of CXCL1, CXCL10 and CXCL13 are distinctly altered in patients with BTC and that serum CXCL13 levels, in particular, represent a promising candidate to predict outcomes following tumor resection." (PMID 36077611, 2022). "Furthermore, the expression levels of CXCL9, CXCL10, CXCL11, and their receptor CXCR3, which perform anti-tumor roles in ICI treatment, were found to have increased in PTPRD/PTPRT mutant cancer patients." (PMID 36248841, 2022). "Notably, TCTP knockdown in A375 P3 cells increased T cell migration and sensitized tumor cells to CTL-mediated killing, which was accompanied by profound changes in CXCL10 and MCL-1." (PMID 35440620, 2022). "Interestingly, a very recent study found that “exhausted” T cells in the tumor microenvironment that were actively recruited via CXCL9 and CXCL10 can also be considered chemokine-producing cells." (PMID 35626062, 2022). "CXCL9, CXCL10, CXCL11 and CCL8 levels were positive correlated with a higher ratio between CD8+ T cells in tumor areas and the total stroma, they might affect the spatial distribution of CD8+ T cells in human pancreatic tumor tissues." (PMID 36479091, 2022). "To determine whether CYLD exerts a similar effect on tumor-intrinsic chemokine production as SPATA2, we transiently knocked down CYLD by RNAi and measured CXCL9, CXCL10, and CXCL11 secretion." (PMID 36531014, 2022). "Moreover, IFN-γ enhances the tumoricidal action of M1 macrophages and the recruitment of NK and T cells from the periphery to the tumor site via CXCL9 and CXCL10 chemokines." (PMID 36428727, 2022). "Here, early production of CCL2 and CXCL1 may help with shaping the initial myeloid cell compartment in cancer-bearing individuals, which promotes tumour development and production of CCL17 and CXCL10 which in turn modulates recruitment of leukocytes." (PMID 35226704, 2022). "Interestingly, while the serum levels of CXCL1 and CXCL10 decreased postoperatively, we observed significantly increased values of CXCL13 after tumor removal." (PMID 36077611, 2022). "CCR5-CCL5 axis was induced to enhance NK cell infiltration in tumor tissue, and CXCR3 on NK cells also could interact with CXCL9, CXCL10, and CXCL11 from tumor cells." (PMID 33918941, 2021). "Therefore, we determined the expression levels of CXCL-9, CXCL-10, CCL-17, and CCL-22 in tumor tissues." (PMID 34620867, 2021). "Importantly, two-way ANOVA demonstrated a significant interaction effect in all markers except Cxcl1, Cxcl9, and Cxcl10, demonstrating the divergent effects that DOX has on cardiac inflammatory markers in tumor-bearing compared to tumor-free mice." (PMID 34445729, 2021). "Both SHP099 and TNO155 upregulated CXCL10 secretion upon rhIFNγ treatment; in addition, SHP2 blockade lowered the dose of rhIFNγ required to affect OVCAR-8 cell viability, indicating that SHP2 inhibition sensitized tumor spheroids to IFNγ." (PMID 33446805, 2021). "CXCL10/IP10, a negative regulator of tumor growth and promoter of CD8+ T cell tumor infiltration in human prostate LNCaP cells, was expressed at comparable levels (~6 pg/mg) in all treatment groups (data not shown), despite low tumor levels of its chief inducer, IFN-γ (fg/mg)." (PMID 34604038, 2021). "Tumor-bearing mice had significantly elevated hepatic expression of the pro-inflammatory cytokines IL-1α, IL-1β, TNF-α, Cxcl9, and Cxcl10 compared to tumor-free mice." (PMID 34445729, 2021). "By reducing Cxcl10 mRNA expression in muscle as well as due to downregulation of circulating CXCL10 level, SIRT6 probably helps to avoid β‐cell destruction, maintaining insulin level and thereby inhibiting tumour progression." (PMID 34212132, 2021).
tumor (continued). "The importance of CXCR3-ligands in the recruitment of tumor-infiltrating lymphocytes (TILs) to the TME had also been demonstrated in several human cancers in which CXCR3+ TILs were abundant and high levels of CXCL9 and CXCL10 were secreted by stromal cells." (PMID 34944943, 2021). "CXCL10 is known to bind to CXCR3, which is also present on mast cells and it is one of the probable reasons for increased infiltration of these cells into the tumor area." (PMID 33436641, 2021). "Certain proinflammatory factors, such as CXCL9, CXCL10, and CXCL16, promote the trafficking of immune cells into the tumor, increase leukocyte chemoattraction and extravasation, and induce tumor surface expression of PD-L1, MHC-I, NK cell ligand, and Fas (CD95) [10,41,57,]." (PMID 34247198, 2021). "Based on this mechanism, it is believed that IL-18 and IP-10/CXCL10 do not exert tumor-suppressive effects, but rather, promote IFN-γ secretion and chemoattraction of CXCR3+ cells into the NPC TME." (PMID 33718235, 2021). "In addition, we observed enhancement of not only CD8+ T cell infiltration but also DC infiltration and upregulation of CXCL9, CXCL10, GZMA, GZMB, and IFN-γ in Col6a1−/− tumor tissues compared with WT MCA205 tumor tissues." (PMID 34782761, 2021). "These fibroblasts can also secrete varied chemokines, such as CXCL9, CXCL10 and CXCL12 which can promote tumor growth and has chemoattractant properties that stimulate the migration of CXCR3+/CXCR4+ suppressive Tregs and cytotoxic T cells into the NPC microenvironment." (PMID 34568077, 2021). "In addition, we found that increased CXCL10, CXCL11, and CXCL13 expression increased survival in patients with OC with tumor progression." (PMID 34794429, 2021). "ICD also requires tumour cell production of pro-inflammatory cytokines Type I interferons (IFN), IL-1β, TNFα and CXCL10, which recruit and activate antigen-presenting cells such as dendritic cells (DCs), natural killer cells (NK, NKT cells) and macrophages, and enhance MHC class I expression." (PMID 34359633, 2021). "Tumor-infiltrating neutrophils can support adaptive immune responses by recruiting T cells to tumor sites via the secretion of chemokines, such as CCL5, CCL20, CXCL9, CXCL10 and CXCL11." (PMID 34572138, 2021). "Likewise, high levels of T cell recruiting and activating IFN-γ induced IP-10/CXCL10 chemokine was induced by EGFR hCART41BBζ, during overnight co-culture with tumor cells at 1:1 E:T ratio compared other hCART, COATC and BATs." (PMID 34290709, 2021). "STRING analysis of leading-edge genes in these macrophage activation signatures, showed that fatty acid stimulation genes upregulated in MAC-MT in tumor were dominated by metallothionine genes, while inflammatory stimulation genes included several chemokines (CXCL9, CXCL10)." (PMID 34936871, 2021). "Moreover, IL-12 facilitates antigen presentation by upregulating MHCI on tumor cells, favoring polarization to M1 macrophages and attracting effector immune cells by enhancing the production of the chemokines CXCL9, CXCL10 and CXCL11." (PMID 33418929, 2021). "Furthermore, EMP3 suppressed T cell infiltration into GBM tumours by inhibiting the secretion of CXCL9 and CXCL10 by macrophages and led to an effective response to anti-PD1 therapy." (PMID 33964937, 2021). "The immune activation of IFN-γ on tumor cells is largely attributed to tumor cells, monocytes, endothelial cells, and fibroblasts inducing tumor cells to express MHC class I and secrete CXCL9, CXCL10, and CXCL11 to promote lymphocyte migration and inhibition of angiogenesis." (PMID 34795663, 2021). "Finally, other approaches point to overexpressing some of the chemokine receptors involved in T cell trafficking to inflammatory sites, such as CXCR3, owing to expression of its ligands, CXCL9 and CXCL10, in the GBM tumor microenvironment (TME)." (PMID 33746981, 2021).
tumor (continued). "Our current working hypothesis is that peripheral administration of CXCL10-Ig or CXCL9-Ig would induce the activity of CXCR3+ effector CD4+ T cells, effector CD8+ T cells, and NK cells that are then recruited to at the tumor sites to limit cancer." (PMID 34944943, 2021). "Immunostaining revealed that circFat1 KD, but not anti‐PD1 treatment, increased the protein levels of CXCL10 in tumor cells of HNSCC." (PMID 34258151, 2021). "Among the main reasons for this failure are the lack of classical T-attractive chemokines (e.g., CXCL9 and CXCL10), the dense tumor microenvironment matrix and the higher tumor-antigen heterogeneity, as compared to hematologic tumors." (PMID 34977027, 2021). "Similar to CXCL10, CXCL11 may play anti-tumor or pro-tumor functions depending on the tissue context." (PMID 34200459, 2021). "In response to interferons, macrophages are polarized and activated into pro-inflammatory classical M1 type that produces cytokines, such as interferon-γ (IFN-γ), tumor necrosis factor-α (TNF-α), IL-23, IL-12, CCL5, CXCL9, CXCL10, and CXCL5 and help destroy tumor cells via activating Th1 cells." (PMID 33925575, 2021). "Furthermore, it is documented that tumor cells with DDR shortage show constitutive triggering of cellular IFN responses and emission of TIL conscripting chemokines, CCL5 and CXCL10." (PMID 34152511, 2021). "CXCL10 upregulation by SHP099/TNO155 treatment was observed exclusively in CD45-negative tumor cells in co-culture but not in immune cells, consistent with scRNAseq data." (PMID 33446805, 2021). "Fusobacterium nucleatum may change tumor proliferation, invasion, metastasis, and drug resistance by increasing the expression of CXCL8 and reducing the expression of CXCL10, thus affecting the prognosis of patients." (PMID 34439306, 2021). "Furthermore, parvoviruses were engineered as vehicles of IFN-γ inducible protein 10 (CXCL10) and TNF-α, showing a synergic effect in tumor regression in rats HGGs models." (PMID 34439595, 2021). "Moreover, we observed that EMP3 affected macrophages, causing inhibition of antitumour immunity via suppression of CD4+ and CD8+ T cell infiltration into GBM tumours and downregulation of CXCL9 and CXCL10 production by macrophages." (PMID 33964937, 2021). "Additionally, some other chemokines controlling T lymphocyte homing to peripheral tissues, such as CCL5, CXCL9, CXCL10, and CXCL11, were also highly expressed in tumours containing large numbers of tumour HEVs." (PMID 33917287, 2021). "Additionally, 968 increases the infiltration of CD3+ T cells into tumors, possibly through enhancing the secretion of CXCL10 and CXCL11 by tumor cells." (PMID 34944392, 2021). "Treatment-driven ICD involves the activation of a cancer cell-intrinsic type I IFN response and consequent secretion of CXCL10 that mediates chemotactic effects of activating immune cells, including cytotoxic CD8+ T-cells and NK-cells, into the tumor microenvironment." (PMID 34944879, 2021). "Two-way ANOVA demonstrated a significant interaction effect between the tumor and DOX in Cxcl10." (PMID 34445729, 2021). "In addition to CXCL10, the injection of anti-IFN-γ also significantly impaired the production of CXCL9 and CCL5 in the tumour microenvironment compared to isotype antibody-treated tumours." (PMID 33925140, 2021). "Moreover, STING-induced IFNI-mediated expression of the ISGs CXCL10 and CCL5 in tumor and immune cells has also been shown to increase NK accumulation and activation in the TME." (PMID 33801234, 2021). "Furthermore, after staining the tumor tissue with CD8, we found that the number of CD8 positive cells in the tumor overexpressing CXCL10 was more than that in the NC group." (PMID 34794429, 2021). "Moreover, in an explorative response prediction model, the combination of protein markers (CXCL9, CXCL10, IL-15, CASP8, and ADA) resulted in higher accuracy in predicting response than tumor PD-L1 expression or each protein assayed individually." (PMID 34206510, 2021).
tumor (continued). "Our laboratory further demonstrated that hedgehog signaling in hepatocellular carcinoma promotes the immunosuppressive M2 phenotype of TAMs, which further impedes CD8+ cytotoxic T lymphocyte trafficking into the tumor stroma via suppression of CXCL9 and CXCL10." (PMID 34771482, 2021). "In non‐tumour‐bearing mice (N.Tu‐CN and N.Tu‐Sk.T6Tg), however, no change in Cxcl10 transcript levels were observed reiterating SIRT6's context‐specificity." (PMID 34212132, 2021). "For example, effector immune cells, such as CD8 + Teff cells, IFN-γ-expressing T helper 1 (TH1) cells and natural killer (NK) cells, can be attracted to the tumor microenvironment by CXC-chemokine ligand 9 (CXCL9), CXCL10 and CXCL11, and exert potent antitumor effects." (PMID 34579759, 2021). "When evaluating clinicopathologic features of tumor in relation to CXCL10 expression, none of the clinicopathologic features were associated with CXCL10 in DCIS." (PMID 34504204, 2021). "Other studies have shown that active CD26 cleaves the chemokine CXCL10 turning it into an antagonist for its cognate CXCR3 receptor, effectively disrupting the chemotaxis that otherwise recruits CXCR3+ effector T-cells to the tumours." (PMID 34016130, 2021). "In addition, cytokines such as CCL5 and CXCL10 may promote cancer cell proliferation by recruiting myeloid cells, and this is essential to activate the immune checkpoint PD-1/PD-L1 axis, which establishes an immunosuppressive tumor microenvironment in multiple cancer types." (PMID 34625086, 2021). "Closer examination of the mechanism of action of GSK126 revealed its ability to promote the expression of IFN-γ driven chemokines CXCL9 and CXCL10 from the tumor cells, that work to traffic T cells without directly affecting T maturation and/or proliferation." (PMID 34336705, 2021). "In another study, Th1-derived IFNγ was shown to increase macrophage-mediated anti-tumor cytotoxic activity by inducing the expression of proteases, granzyme A/B, and NK cell-related genes (e.g., NKG2D) and by promoting CXCL9 and CXCL10 secretion by macrophages." (PMID 33801234, 2021). "Moreover, their cognate ligands, including CCL2, CCL3, CCL4, CCL5, CXCL9, CXCL10, and CXCL11, are often upregulated in a range of different tumour types." (PMID 34885108, 2021). "Confirming TBK1 vs. IKKα/β dichotomy of mRIPO vs. LPS treatment, tumor homogenate cytokine analysis revealed stronger IKKα/β-driven cytokine induction by LPS (IL-6, TNF, IL-1β, IL-10), with CXCL10 (TBK1-dependent) being the most prominently induced cytokine after mRIPO treatment." (PMID 33767151, 2021). "Indeed, the majority of human PDAC tumors contain a subset of tumor cells expressing CXCR3 and exposure to CXCL10 induced resistance to gemcitabine." (PMID 34203869, 2021). "As a consequence, suppression of VEGF signalling pathway by the treatment with sunitinib in tumour-bearing mice led to pronounced upregulation of CXCL10 and CXCL11 in tumour blood vessels, accompanied by a robust increase in the infiltration of leucocytes in tumours." (PMID 33917287, 2021). "Additionally, CXCL9 and CXCL10 are also expressed by M1-polarized TAMs and CXCL11 can be found on tumor vasculature." (PMID 34203660, 2021). "The levels of CXCL10 in tumor/non-tumor tissue (p = 0.0148, p = 0.0111) and TLR4 (p = 0.0343) in non-tumor tissue, but not CXCR3, were significantly higher in small-for-size graft than whole graft post-transplantation with tumor recurrence." (PMID 33990548, 2021). "One of the possible explanations for such discrepancy is that perhaps even though the direct effect of CXCL10 and CXCL9 on effector T cells, and possibly endothelial cells is similar, their direct effect on tumor cells may vary." (PMID 34944943, 2021).
tumor (continued). "In our laboratory, we demonstrated that tumor-derived sonic hedgehog (Shh) ligand promotes M2-polarization of TAMs to suppress CD8+ T cell infiltration through downregulation of CXCL9 and CXCL10 and limit effector T cell functions by upregulating programmed death ligand-1 (PD-L1) expression on TAMs." (PMID 34771482, 2021). "The anti-tumor “N1” phenotype exhibited increased tumor cytotoxicity, elevated expression of CXCL13, CCL3, CCL6, CXCL10, TNFα and ICAM-1 and low ARG1 content, while the pro-tumor “N2” neutrophils expressed high levels of ARG1, MMP9, VEGF and several cytokines, including CCL2, CCL5, CCL17 and CXCL4." (PMID 34572138, 2021). "Notably, the CXCL9/CXCL10/CXCL11/CXCR3 axis recruits cytotoxic lymphocytes, NK cells, NKT cells, and macrophages to infiltrate tumor tissue and increases cytotoxic activity against tumor cells." (PMID 33763074, 2021). "Consequently, elevated PD-L1 expression as well as T-cell recruitment by proinflammatory cytokine CXCL10 and CCL5 occur in the tumor microenvironment." (PMID 34630387, 2021). "We found that treatment with SHP099 led to increased expression of three CXCR3 ligands, the chemoattractant cytokines CXCL9, CXCL10 and CXCL11 specifically in tumor cells in co-culture, with CXCL10 showing the most significant upregulation and magnitude of expression." (PMID 33446805, 2021). "Anti-tumor immune response by IFN-γ can also be elicited by recruitment of additional effector cells, namely NK cells and M1 macrophages to the TME, facilitating T-cell homing through CXCL9 and CXCL10 chemokines, and via enhanced CD8+ cytotoxicity in the TME." (PMID 34012451, 2021). "CXCR3+ T cells and NK cells recruited to the TME by IL-18 and IP-10/CXCL10 are unlikely to possess anti-tumor function, although they are active in IFNγ production." (PMID 33718235, 2021). "In addition, CXCL10, CXCL9, and CXCL11 production is induced in the tumor microenvironment, which recruits cytotoxic lymphocytes (CTLs) and reduces tumor angiogenesis, inducing further tumor death." (PMID 33807260, 2021). "In our data, Mø_c1 represented the most abundant macrophages (37.10%) with high expression of IL1B, as well as CXCL10 and CXCL9, which might be involved in anti-tumor responses." (PMID 33298893, 2020). "CEA-TCB-treated tumors displayed a clear upregulation of several pro-inflammatory cytokines and chemokines [MIPα (CCL3), CXCL10, CXCL13, CXCL9, IL-16, and I-TAC (CXCL11)], an increase in intra-tumor CD3+, CD4+, CD8+ T-cells that express high levels of 4-1BB, PD-1, and upregulation of GZMB." (PMID 33330050, 2020). "The combination of PDT and FlaB-Vax also enhanced the infiltration of tumor antigen-reactive CD8+ T cells and the accumulation of migratory CXCL10-secreting CD103+ dendritic cells (DCs) presumably contributing to tumor antigen cross-presentation in the tumor microenvironment (TME)." (PMID 33171765, 2020). "qPCR results showed that levels of chemokines (CXCL10, CCL5, IFN-β) were increased after silencing of TAZ in CALU-3, NCI-H520, and M109 at the presence of STING pathway agonist cGAMP and in SKIL-silenced NSCLC cell-derived tumor blocks." (PMID 33268765, 2020). "According to expression profiles across all tumor samples and paired normal tissues in GEPIA, the log2-fold change in expression of CXCL10 in DLBCL relative to that of paired normal tissues was significantly higher than that of any other type of tumor versus normal." (PMID 33240622, 2020). "CXCL10 was major secreted by pancreatic stellate cells and could be delivered to PAAD tissue to foster an immunosuppressive tumour microenvironment." (PMID 31913856, 2020). "Interestingly, in contrast to STING knockout in LKB1-reconstituted H1355 spheroids, STING knockout in HUVECs consistently resulted in impaired production of CXCL10 in 3D MVN co-culture, despite only treating tumor cells with poly-(dA:dT)." (PMID 33013881, 2020).